Y_RNA (Y RNA )
Gene: Miscellaneous RNA gene on chromosome 18 (34,001,698 to 34,001,799, reverse strand). Ensembl gene ENSG00000199204.
Homologues: Orthologues: chimpanzee Y_RNA (95% identical), macaque Y_RNA (95% identical). Paralogues in human: Y_RNA (90% identical), Y_RNA (88% identical), Y_RNA (87% identical), RNY3 (86% identical), Y_RNA (86% identical), RNY3P1 (85% identical), Y_RNA (85% identical), Y_RNA (84% identical), RNY3P16 (83% identical), Y_RNA (83% identical), RNY3P11 (82% identical), Y_RNA (82% identical), and 96 more.